ZNF22-AS1 (ZNF22 antisense RNA 1)
Synonyms: C10orf25; FLJ30567
Gene: Long non-coding RNA gene on chromosome 10 (44,997,697 to 45,236,093, reverse strand). Ensembl gene ENSG00000165511.
Subcellular location: Secreted
Diseases named in the same sentence as ZNF22-AS1 in open-access papers:
ZNF22-AS1 is named in the same sentence as 1 disease in open-access papers, as found by Europe PMC text mining. Sharing a sentence is not in itself a finding about the gene and the disease.
ZNF22-AS1 shares sentences with these, for which no sentence is quoted: cancer (1 paper).